CCL2 (C-C motif chemokine ligand 2)
Diseases named in the same sentence as CCL2 in open-access papers (continued):
Sharing a sentence is not in itself a finding about the gene and the disease.
schizophrenia (39 papers, 2010 to 2025). A major psychotic disorder characterized by abnormalities in the perception or expression of reality. "Our results showed that three polymorphisms, regulating positively the expression of the CCL2 chemokine, could have a protective effect on the schizophrenia susceptibility." (PMID 31886209, 2019). "In contrast, the schizophrenia group had a much lower level of CCL2 than the control group (p < 0.001)." (PMID 41200225, 2025). "It is worth mentioning that in the ‘microglia hypothesis’ of schizophrenia, the disease occurs in MS patients with a prevalence (> 60%) of associated frontotemporal lesions, a pathogenesis supported by the demonstrated CCL2-driven microgliosis observed in the neocortex of EAE-affected mice." (PMID 36042496, 2022). "Activation of TLR3 leading to an upregulation of IL-1β, CCL2, and CXCL10 are also seen in models of autism and schizophrenia associated with white matter abnormalities." (PMID 33558485, 2021). "Suggestive associations were observed for the SNPs rs4795893 and rs4586 with the gene CCL2 in drug response in less severely ill schizophrenia patients." (PMID 26788534, 2016). "Finally, macrophage recruitment chemokine CCL2 mRNA was increased in schizophrenia (>200%, p < 0.0001) and CCL2 mRNA levels positively correlated with CD163 mRNA (r = 0.46, p < 0.0001)." (PMID 35844224, 2022). "Robust data, supported by meta-analyses, indicate elevated levels of CXCL8/IL-8, CCL2/MCP-1, CCL4/MIP-1β, and CCL11/eotaxin-1 in the bloodstream of individuals with schizophrenia." (PMID 41303622, 2025). "Meta-analyses data showed an increase in CXCL8/IL-8, CCL2/MCP-1, CCL4/MIP-1β, and CCL11/eotaxin-1 in the blood of patients with schizophrenia." (PMID 39457671, 2024). "This study aimed to examine serum levels of Th17-related cytokines (IL-17, IL-21, IL-22, IL-23) and chemokines (CCL2, CCL5, CCL20, CXCL10, IL-8) in schizophrenia patients compared to healthy controls and to explore their associations with symptom severity and laboratory parameters." (PMID 41200225, 2025). "Furthermore, heightened neurotoxicity resulting from elevated concentrations of toxic cytokines (e.g., IL-1β, IL-6, IL-8, TNF-αand IFN-γ) and chemokines (e.g., CCL11, CCL2, CXCL8 and CXCL10) is markedly correlated with the schizophrenia phenome." (PMID 41200225, 2025). "Besides, the most reliable data confirmed by the results of meta-analyses showed an increase in CXCL8/IL-8, CCL2/MCP-1, CCL4/MIP-1β, CCL11/eotaxin-1 in the blood of patients with schizophrenia." (PMID 36768537, 2023). "Therefore, elevated pro-inflammatory cytokines may promote CCL2 expression, macrophage transmigration, and macrophage differentiation into a more pro-inflammatory phenotype and may propagate a feed-forward cycle of inflammation in the prefrontal cortex or people with schizophrenia." (PMID 35844224, 2022). "CCL2 was also identified as a trait marker (defined here as elevated in both first- and multiple-episode schizophrenia patients irrespective of treatment) in another recent meta-analysis." (PMID 32010121, 2019). "Importantly, MCP-1 (CCL2) serum levels were higher in first-episode psychosis and multiple-episode schizophrenia, while MIP-1β (CCL4) and eotaxin-1 (CCL11) levels were higher only in multiple-episode schizophrenia." (PMID 35546942, 2022). "CCL2, coming from either myeloid cells or astrocytes, can influence the differentiation of tissue macrophages and promotes the production of proinflammatory cytokines including IL-6, IL-1β, and TNF-α which are all elevated in the brains of people with high inflammation schizophrenia." (PMID 35844224, 2022). "We hypothesized that the macrophage recruitment chemokine (CCL2/MCP-1), and the macrophage-derived chemokine IL-8 would be elevated in the high inflammation schizophrenia cortex, and we performed regression analysis to predict which macrophage types are more related to CCL2." (PMID 35844224, 2022).
schizophrenia (continued). "In particular, analyses revealed an increased number of monocytes and elevated levels of CCL2 in the first-episode psychosis (FEP) patients and multiple-episode schizophrenia (MES) individuals, suggesting that this chemokine may contribute to the development of this disorder." (PMID 31886209, 2019).
ZIKV infection (39 papers, 2018 to 2025). "CCL2 levels, reported to be associated with neuronal degeneration, were downregulated at both the 24- and 48-hpi timepoints during ZIKV infection, and the 96-hpi HCMV infection timepoint." (PMID 38440980, 2024). "In addition, ZIKV infection caused increased levels of cTnT, cTnI, CK, CK-MB, CCL2, CXCL9, and CXCL10—biomarkers associated with cardiovascular diseases and infarction-like myocardial pathology." (PMID 40762502, 2025). "In particular, the CCL2-201 isoform was shown to be elevated in early acute infection and then decreased in the late acute and convalescent stage of ZIKV infection." (PMID 39065267, 2024). "Of particular interest, the elevated level of CCL2, along with its inverse correlation with CD163, TNFRSF1A, and CCL22 levels, was associated with abnormal births following ZIKV infection." (PMID 38137537, 2023). "These authors revealed that the chemokines CXCL10, CCL2, and CCL8 were specifically associated with symptomatic ZIKV infection during pregnancy, and distinct immunoprofiles were detected in different trimesters in ZIKV-infected pregnant women." (PMID 33525328, 2021). "We show that ZIKV infection activates proinflammatory (IL-1β) cytokines as well as chemokines (CCL2, CCL5, GM-CSF, G-CSF, CXCL1, and CXCL12) in the endothelial cells." (PMID 31249527, 2019). "Notably, ZIKV infection led to a 72-fold and 104-fold increase in CCL2 (marked with a red asterisk in 3A) and CXCL10 (notified by a black asterisk in 3A) levels, respectively." (PMID 40762502, 2025). "Notably, chemokines such as CXCL10, CCL2, and CCL8 were associated with symptomatic ZIKV infection during pregnancy." (PMID 38137537, 2023). "ZIKV infection increases the levels of a series of cytokines (IL-1α, IL-6, IL-9, IL-10, IL-12p70, and IFN-γ) and chemokines (CCL2, CCL3, CCL4, CCL5, CCL11, and CXCL1) in mouse brain." (PMID 34399779, 2021). "Our results are consistent with the characteristic pattern of circulating CXCL10, CCL2, and CXCL9 chemokines during ZIKV infection." (PMID 33430059, 2021). "Despite the increased production of CCL2, the density of Iba1+/TMEM119− myeloid cells and their ratio over Iba1+ cells were unaffected during ZIKV infection." (PMID 34399779, 2021). "Increased serum concentrations of both CXCL (CXCL8 and CXCL10) and CCL chemokines (CCL2, CCL3, CCL4, CCL5, and CCL11) were found in acute ZIKV infection." (PMID 29768624, 2018). "Acutely infected cells produced high levels of pro-inflammatory chemokines, including CCL2, CCL3, CCL4, CCL5 and CXCL8, which could contribute to CNS inflammation during ZIKV infection in vivo by promoting the recruitment of various leukocytes into the CNS." (PMID 32375993, 2020). "In our study, levels of several immune markers, such as IFN-α, IL-12, IL-6, IL-17, IL-10, IL-5, IL-2R, ST2/IL-1R4, CCL2, CCL3, CXCL9, M-CSF and E-Selectin, were significantly higher in presymptomatic/asymptomatic ZIKV infection (A-ZIKV group) when compared to the NI control group." (PMID 31748599, 2019). "Importantly, CCL2, CCL5, CXCL9, and CXCL10 were consistently elevated in both serum and heart tissue, indicating a systemic and localized inflammatory response induced by ZIKV infection." (PMID 40762502, 2025). "The samples from pregnant women with ZIKV infection included in this study showed increases in all anti-inflammatory cytokines (IL-10), and some pro-inflammatory cytokines (IL-6, IFN-γ, IFN-α, and IL-17A), chemokines (CXCL10, CCL2, CXCL9, and CXCL8), and receptors (IL-1RA and IL-2R)." (PMID 33430059, 2021).
Allergy (38 papers, 2010 to 2025). An allergy is an immune response or reaction to substances that are usually not harmful. "We have previously shown that the serum levels of CCL2 increase during acute allergic reactions, with high levels correlating with CCL2‐mediated basophil chemotaxis and significant migration of circulating basophils." (PMID 39988712, 2025). "The chemokine CCL2, which is an effective attractant for monocytes, was significantly increased in the allergy model, whereas surprisingly CCL11, a signaling molecule attracting eosinophils was significantly decreased in the serum of allergic mice." (PMID 27445696, 2016). "Hence, the findings suggest a dual role for MC‐derived CCL2 in allergic reactions, wherein its production not only influences basophil migration but also affects endothelial cell barrier function by modulating vascular permeability." (PMID 39988712, 2025). "Altogether, these findings show a persistent systemic inflammation in children with microcephaly due to CZS and suggest a possible impairment in leukocyte migration caused by low production of CCL2 and CXCL8, in addition to high levels of IgE associated with high prevalence of allergies." (PMID 37766239, 2023). "Therefore CCL2-mediated migration might represent a unique mechanism for the selective migration of human basophils in allergic reactions." (PMID 28342911, 2017). "The analysis implicated a number of genes with roles in allergy and inflammation, including pro-inflammatory cytokines (IL1A, IL1B, IL6, IL8 and TNF) and factors involved in immune cell activation and recruitment (SELE, SELL, SELP, ICAM1, CSF2, CSF3, CCL2 and CXCL2)." (PMID 21067579, 2010). "In addition to CCL2, several other chemokines might be involved in different allergic diseases." (PMID 33317619, 2020). "It promotes Th2 cell differentiation in allergic diseases while inhibiting chemokine Ccl2 expression and NF-κB activity, thereby mediating negative regulation of the innate immune response." (PMID 40416976, 2025). "RASD2, IL24, CCL2 and CCL7 are immunologically relevant biomarkers in allergy." (PMID 33849432, 2021). "Therefore, it is tempting to speculate that CCL2 might be mast cell derived and that circulating basophils influx to the sites where the activation and degranulation of mast cells occur, thereby contributing to the clinical presentation of the sites of allergic reaction." (PMID 33317619, 2020). "did provide a proof that acteoside could alleviate inflammatory response by down-regulating the expression of CCL1, CCL2, CCL3 and CCL4 in allergy." (PMID 29708439, 2018). "Peanut-induced allergic reactions resulted in a significant decrease in circulating basophil counts compared with those in prechallenge samples (P = .016), a decrease in FCER1A expression (P = .007), and an increase in CCL2 levels (P = .003)." (PMID 28342911, 2017). "LTC4, IL-6, IL-1, MCP-1/CCL2, and TNF-α play important roles in the development of allergic diseases, and their release and synthesis could be increased in various allergic diseases." (PMID 27200102, 2016).
glomerulonephritis (38 papers, 2009 to 2025). A renal disorder characterized by damage in the glomeruli. "CCL2, one of the key chemokines produced by renal and immune cells in response to kidney injury, was also found to be associated with glomerulonephritis in humans and mice." (PMID 36510250, 2022). "For example, the chemokine CCL2 was upregulated already 3 hours after induction of glomerulonephritis by an anti-thymocyte antibody in rats, and anti-CCL2 antiserum reduced neutrophil and monocyte/macrophage accumulation in the injured kidney." (PMID 35203629, 2022). "In the context of renal pathophysiology, CCL2 participates in glomerulonephritis (GN), DN, and the CKD model of unilateral ureter obstruction (UUO)." (PMID 35806457, 2022). "These elevated CCL2 levels in the kidneys are also reportedly involved in the progression of tubulointerstitial fibrosis, glomerulonephritis, and massive proteinuria accompanied by monocyte and macrophage recruitment in the kidneys in rats." (PMID 33159802, 2021). "In our present glomerulonephritis model study, we detected CCL2 levels as total CCL2 levels using a purchased ELISA kit that detects epitopes other than pE-N-terminal amino acids." (PMID 33159802, 2021). "CCL2 expression in kidney was also significantly increased at necropsy in the glomerulonephritis rats." (PMID 33159802, 2021). "Indeed, antibody-mediated neutralization of CCL2 was previously shown to reduce the development of kidney fibrosis in nephrotoxic serum-induced glomerulonephritis." (PMID 35203629, 2022). "In addition, total CCL2 concentration in serum and urine was significantly increased in the glomerulonephritis rats beyond 2 weeks after the injection of anti-GBM serum." (PMID 33159802, 2021). "In a glomerulonephritis mouse model, CCL2 plays a role in crescent formation and interstitial fibrosis supported by the observation that anti-CCL2 antibodies can reduce crescent formation, renal impairment, and scarring, as well as T cell and macrophage infiltration." (PMID 24451065, 2014). "In the glomerulonephritis rats, the mRNA levels of CD68 and CCL2 in the kidney cortex were significantly increased at necropsy and significantly suppressed by repeated administration of PQ529 in a dose-dependent manner." (PMID 33159802, 2021). "Treatment with anti-CCL2 antibodies and CCR2 inhibitors suppresses urine protein leakage and inflammation in the tubulointerstitium and glomeruli and decreases the migration of macrophages into these tissues in a rat model of glomerulonephritis." (PMID 33159802, 2021). "Inflammatory processes in glomerulonephritis strongly depend on the pro-inflammatory chemokines CXCL8 (interleukin-8 (IL-8)), CCL2 (monocyte chemotactic protein-1 (MCP-1)) and CXCL2 (macrophage inflammatory protein-2α (MIP-2α)) to direct neutrophils and macrophages towards the glomerulus." (PMID 30248108, 2018). "Real-time PCR analysis of whole kidneys identified a marked increase in the gene expression of leukocyte markers (CD68, CD3e), proinflammatory cytokines (TNF-α, IFN-γ, CCL2) and macrophage elastase (MMP-12) in untreated and vehicle-treated mice at day 15 of glomerulonephritis." (PMID 26700873, 2015). "We confirmed in the present study that the degree of decrease in CCL2 protein in the kidney was similar to the degree of decrease in the infiltration of mononuclear cells into the kidney, as shown by our comparison of the control and PQ529-treated glomerulonephritis rats." (PMID 33159802, 2021). "Notably, increased leukocyte recruitment and increased expression of IL-6 and CCL2 in the absence of Sdc1 have been observed in other in vivo models of inflammation, including delayed-type hypersensitivity, glomerulonephritis, and autoimmune encephalomyelitis." (PMID 28350804, 2017).
Parkinson disease (38 papers, 2011 to 2026). A progressive degenerative disorder of the central nervous system characterized by loss of dopamine producing neurons in the substantia nigra and the presence of Lewy bodies in the substantia nigra and locus coeruleus. "Furthermore, reduced plasma levels of CCL2 were identified in patients with mutations in the GBA gene that encodes the enzyme beta-glucocerebrosidase, in comparison with sporadic Parkinson’s disease patients and controls." (PMID 36613708, 2022). "MCs-derived CCL2 could result in the elevated levels of CCL2 observed in animal model of Parkinson's disease." (PMID 31552201, 2019). "Thus, one can hypothesize that an accumulation of glucosylceramides or GM2 in Parkinson’s disease could participate to the production of CCL2 and to the recruitment of CCR2+ leucocytes into the brain." (PMID 33069254, 2020). "Parkinson’s Disease pathogenesis is also thought to involve down-regulation of nuclear receptor Nurr1 in microglia and astrocytes, leading to increased production of mediators such as chemokine CCL2 that may promote apoptosis of dopaminergic neurons." (PMID 31133804, 2019). "CCL2, by reducing glutamate levels increased by N-methyl-d-aspartate (NMDA) and Tat protein, and IL-6, by preventing ROS and Ca2+ excitotoxicity in Parkinson’s and Huntington’s diseases, exert neuroprotective properties." (PMID 29228979, 2017).